ROR2 (ROR family WNT receptor 2)
Diseases named in the same sentence as ROR2 in open-access papers (continued):
Sharing a sentence is not in itself a finding about the gene and the disease.
tumor (continued). "Overall, these results demonstrate that the molecular characterization of the evolution from normal T lymphocytes to in vivo NA models enabled the identification of ROR2 as a relevant cell surface marker of ALK+ ALCL tumor cells." (PMID 35246138, 2022). "ROR2 was shown to either suppress or promote tumor progression in different tumor types by regulating the same biological processes (i.e. proliferation, invasion) in opposite ways." (PMID 36127680, 2022). "In contrast, the expression of ROR2 and its participation in several tumor types have been more extensively documented." (PMID 36127680, 2022). "For example, ROR2 has a tumor-suppressive function in endometrial and colon cancer, in medulloblastoma, and hepatocellular and gastric carcinoma." (PMID 36127680, 2022). "CCT301-38 will target AXL on tumor cells while CCT301-59 will target receptor tyrosine kinase-like orphan receptor 2 (ROR2) antigens in tumors." (PMID 35775004, 2022). "The bone marrow of patients with low levels of ROR2 disrupted Wnt5a signalling produced by the osteoblastic niche, which hinted at the potential development of osteolytic tumours in bone." (PMID 36307871, 2022). "Taken together, these studies point to a specific role for ROR2 in invasive growth and metastasis of the named tumor entities." (PMID 33445713, 2021). "The role of ROR2 in tumor growth was assessed in xenotransplantation experiments followed by immunohistochemistry analysis of the tumors." (PMID 34774050, 2021). "The Wnt signalling receptor ROR2 has been shown to play distinct roles in regards to tumorigenesis in different tumour types." (PMID 33494187, 2021). "Compared to adjacent normal tissue samples (n = 52), the gene expression level of ROR2 was significantly lower in tumour tissue (n = 553) in the TCGA-UCEC cohort." (PMID 33494187, 2021). "We then aimed at further elucidating the consequences of the WNT11/ROR2 interaction for tumor cell function." (PMID 34911552, 2021). "Tumors with high ROR2 expression by IHC showed a high primary tumor stage (p < 0.001), high histological grade (p < 0.001), and vascular invasion (p = 0.045)." (PMID 34440262, 2021). "ROR2 plays a tumour-suppressor role in EC and is epigenetically suppressed with the development of disease." (PMID 33494187, 2021). "We found that ROR2 was downregulated in EC tumour tissue compared to the adjacent normal tissue, and that this gene silencing was associated with tumour grade." (PMID 33494187, 2021). "ROR2 has been reported to play either an oncogenic or tumour suppressor role based on different tumour context and appears more tightly linked to metastasis than proliferation." (PMID 34763666, 2021). "The present manuscript shows that ROR2 has a far more complex role than originally described and can even have both pro- and anti-tumorigenic roles in the same tumor type." (PMID 34774050, 2021). "On the other hand, ROR2 has a tumor-suppressive function in endometrial and colon cancer as well as in medulloblastoma and hepatocellular, and gastric carcinoma." (PMID 34774050, 2021). "Apart from the primary tumor tissue, high levels of ROR2 were detectable in lymph node and brain metastases, thus suggesting its involvement in tumor progression and metastasis." (PMID 34911552, 2021). "ROR2 has been reported to act either as a tumor suppressor or an oncogene depending on the type of tumor." (PMID 34911552, 2021). "Xenotransplantation experiments demonstrated that ROR2 also reduces proliferation in vivo, resulting in inhibition of tumor growth." (PMID 34774050, 2021). "The functional consequences of WNT11/ROR2 signaling for tumor cell aggressiveness were assessed by microscopy, impedance sensing as well as viability and invasion assays." (PMID 34911552, 2021). "This article analyzes publicly available gene and protein expression data and reveals the existence of a WNT5A/FZD2/FZD7/ROR2 signature, which correlates with tumor-infiltrating and mesenchymal cell marker expression." (PMID 33869179, 2021).
tumor (continued). "Together, these results indicate that ROR2 promotes BC tumor growth by regulating the expression of apoptotic and PI3K/AKT signaling genes." (PMID 32614787, 2020). "The ROR2 expression in siROR2-formed tumor tissues was significantly lower than in control or siRNA groups, while the ROR2 expression in pLenti-ROR2-formed tumor tissues was higher than in control or pLenti vector groups." (PMID 32614787, 2020). "In contrast, the role of ROR2 in carcinogenesis remains controversial as it acts as either a tumour suppressor or tumour promoter in different cancers." (PMID 32807831, 2020). "Silencing ROR1 or ROR2 in different tumour types has been shown to inhibit proliferation and decrease metastatic potential." (PMID 32807831, 2020). "The ROR2 gene expression was significantly increased in BC tissues compared with corresponding non-tumor tissues (P<0.01)." (PMID 32614787, 2020). "In contrast, the tumor volumes were markedly increased in the MCF-7-pLenti-ROR2 group compared with control or pLenti vector groups." (PMID 32614787, 2020). "Analysis of ROR2 mRNA levels in 45 BC tissues and adjacent non-tumor tissues revealed that ROR2 expression was significantly increased in BC tissues, and that it correlated with tumor diameter." (PMID 32614787, 2020). "Our study demonstrates that ROR2 suppression reduces BC cell proliferation and tumor growth in vitro and in vivo, and induces apoptosis of BC cells by regulating the PI3K/AKT pathway." (PMID 32614787, 2020). "Nevertheless, mass of contrary results brought the tumor promoter definition of ROR2 into controversy." (PMID 31878941, 2019). "Compared with the opinion that ROR2 works as tumor promoter in initial studies, more and more researches show ROR2 plays dual roles in tumors depending on tumor type and tumor context." (PMID 31878941, 2019). "As the study processed, more and more evidences indicate the complexity of the role of ROR2 in tumor initiation and progression." (PMID 31878941, 2019). "Findings above indicated ROR2 played dual roles in tumors depending on the tumor type and tumor context." (PMID 31878941, 2019). "Through inhibiting this canonical Wnt signaling as a gatekeeper, ROR2 has been proposed to play a role in tumor suppression." (PMID 31798639, 2019). "We then find that IFT20 mediates the ability of Ror2 to promote the invasiveness of these tumor cells." (PMID 28127051, 2017). "We further considered that Ror2 signaling has been shown to suppress canonical Wnt signaling in these tumor cells." (PMID 28127051, 2017). "Initially examining SaOS2 cells as a model tumor, we find that Ror2 signaling promotes the expression of IFT20." (PMID 28127051, 2017). "Here, we uncover a new non-ciliary role of IFT20, acting to regulate Golgi structure and transport, and also find that this role mediates the ability of constitutively activated Ror2 signaling to promote tumor invasiveness." (PMID 28127051, 2017). "Analysis of 239 primary tumour samples from a publicly available cohort also found a significant correlation between reduced ROR2 expression and increased promoter methylation." (PMID 27440078, 2016). "To determine if ROR2 expression was also reduced in primary tumour samples, we examined publicly available data from The Cancer Genome Atlas (TCGA)." (PMID 27440078, 2016). "PTL tumor tissues showed Wnt5a+ and Ror2+ staining in 12 (54.5 %) and 18 (81.8 %) cases, respectively." (PMID 26608372, 2016). "Data from 12 paired CRC patient samples showed that on average, 11 of the patient primary tumours had a twofold decrease in ROR2 expression compared to the normal mucosa samples (P < 0.01)." (PMID 27440078, 2016). "Both publications used qRT-PCR to document ROR2 expression in 20 matching tumour and normal samples yet report different findings." (PMID 27440078, 2016). "ROR2 suppression reduced invasiveness of an LMS cell line in vitro and ROR2 knockdown resulted in smaller tumor volumes in xenograft models." (PMID 26576131, 2015).
tumor (continued). "Third, the IHC data is semiquantitative, additional methods are needed to evaluate and confirm the expression level of ROR2 and Wnt5a in tumor cells." (PMID 26305508, 2015). "Univariate analysis showed that cytoplasmic ROR2 expression, Wnt5a expression, tumor TNM stage, tumor status, lymph node metastasis, and combined ROR2 and Wnt5a expression level were correlated with overall survival of NSCLC patients." (PMID 26305508, 2015). "Multivariate analysis further demonstrated that ROR2 expression (P < 0.001), Wnt5a expression (P = 0.003) and tumor TNM stage (P = 0.002) were independent prognostic factors." (PMID 26305508, 2015). "ROR2 expression was also elevated in tissue sections from patients with borderline tumours compared to benign controls (p = 0.017)." (PMID 26515598, 2015). "A possible interaction of PTK7 with Ror2 is likely not limited to NC cells, as PTK7 and Ror2 have also been implicated in tumor development and progression." (PMID 26680417, 2015). "Positive staining of ROR2 was primarily localized in the tumor cell cytoplasm and stromal cells of PDAC." (PMID 26259918, 2015). "Prior work in RCC has shown that suppression of Ror2 with shRNA in RCC cells orthotopically injected into the kidney resulted in a dramatic reduction of tumor growth in vivo." (PMID 25542006, 2014). "Our analysis showed a significant enrichment in high Ror2 expressing human ccRCC tumors with high nuclear grade and high clinical/tumor stage, markers for tumor progression." (PMID 25542006, 2014). "To determine if our findings with Ror2 promoting aggressive features of tumor growth, cell migration, and cell invasion translated into promoting tumor progression in ccRCC patients, we turned to the recently published TCGA ccRCC dataset." (PMID 25542006, 2014). "Our results cannot exclude either of these possibilities and, as such, further studies are needed to more fully elucidate Ror2's role as a kinase and its signaling cascades in promoting tumor growth and invasion in RCC." (PMID 25542006, 2014). "We sought to further elucidate the role of Ror2 as an additional tumor promoting component in ccRCC, focusing on its effects in enhancing tumor cell invasive features." (PMID 25542006, 2014). "High expression of Ror2 showed a significant correlation with higher clinical stage, nuclear grade, and tumor stage." (PMID 25542006, 2014). "Mutations in key regions of the kinase domain of Ror2 resulted in the abrogation of increased tumor growth, cell migration, and cell invasion observed with expression of wild-type Ror2." (PMID 25542006, 2014). "We show that overexpression of Ror2 in RCC cells resulted in increases in tumor growth as determined by average daily tumor size, as well as the observation of increased local invasion of xenograft tumors." (PMID 25542006, 2014). "Consistent with our findings with the orthotopic model, we observed a significant increase in tumor size with expression of wild-type Ror2 over the control." (PMID 25542006, 2014). "We also explored the effects of Ror2 overexpression in tumor xenograft growth, and in The Cancer Genome Atlas (TCGA) ccRCC tumor datasets to determine how Ror2 expression related to clinical outcomes." (PMID 25542006, 2014). "Following our observations of Ror2 leading to increased tumor growth and invasion in vivo, we sought to more fully elucidate the role of Ror2 mediating cell migration and invasion in RCC." (PMID 25542006, 2014). "ROR2 is tyrosine-kinase receptor that plays an important role in developmental morphogenesis and in our network it was activated by the tumor-secreted WNT5A, a WNT pathway signaling mediator." (PMID 24597571, 2014). "We detected methylation at the ROR2 promoter in 14 of the 36 tumours (38.8%), which confirmed that this is a common event in vivo." (PMID 20591152, 2010). "Depending on the tumour type, ROR2 signals can therefore show a preference for β-catenin/TCF-dependent genes or for non-canonical Wnt pathways." (PMID 20591152, 2010).
tumor (continued). "ROR2 is a transmembrane protein RTK enriched in several tumor types." (PMID 41018114, 2025). "ROR2, also a non-canonical Wnt receptor, has been implicated in tumour invasiveness, although its direct link with hypoxia in PCa still requires further studies." (PMID 41007281, 2025). "Interestingly, high expression of ROR1, ROR2, and FZD2 were associated with a higher proportion of T cell‐inflamed tumor." (PMID 38558536, 2024). "After establishing the mechanism of how ROR2 can be transferred to neighboring cells in the tumor microenvironment, we asked the question of whether transferred ROR2 remains active." (PMID 37722040, 2023). "On the other hand, the role of ROR2 in tumor development depends on the type or stage of the tumor." (PMID 38077251, 2023). "Studies have shown that ROR2 may regulate the balance of Wnt signaling and cellular heterogeneity during tumor progression." (PMID 37029329, 2023). "High ROR2 expression usually leads to tumor aggressiveness and poor prognosis." (PMID 37174750, 2023). "We found that all tumor cells share the vast majority of these mutations (i.e., they are clonal), including variants affecting genes previously associated with CRC progression (e.g., INPP1, CDC5L, ROR2, EXOSC5)." (PMID 35081992, 2022). "Alternatively, dormant tumour cells could also aberrantly increase the expression of several genes, such as ROR2, Axl and TANK binding kinase 1 (TBK1), to facilitate osteoblast-induced tumour cell dormancy." (PMID 36307871, 2022). "High ROR2 gene mRNA expression had a large tumor size and reducedthe disease-free survival rate." (PMID 34440262, 2021). "Interestingly, the expression levels of ROR2 increased even further in metastatic tissue compared with matched primary tumor samples." (PMID 33445713, 2021). "Moreover, high ROR2 immunoexpression significantly correlated with high tumor stage, high tumor grade, lymph node metastasis, and vascular invasion (all p < 0.05)." (PMID 34440262, 2021). "Interestingly, the two most prognostically contrasted tumor clusters in this cohort markedly differed in ROR2 expression." (PMID 34774050, 2021). "In contrast, our previous study suggested a potential tumour suppressor role for ROR2 in EC." (PMID 33494187, 2021). "One potential candidate might be BA3021, a CAB-ROR2-ADC, which reversibly interacts with ROR2 in conditions reflecting the tumor microenvironment, but less so in normal tissue." (PMID 33445713, 2021). "ROR2 has been reported to act as a tumour promoter or suppressor depending on tumour type." (PMID 33494187, 2021). "In addition, our results show that ROR2 induces BC cell proliferation and tumor growth in vitro and in vivo, and that the mechanism involves activation of the PI3K/ATK signaling pathway." (PMID 32614787, 2020). "However, we found a moderate correlation between ROR2 expression and tumour grade in our cohort (p = 0.079)." (PMID 32807831, 2020). "Importantly, ROR2 suppression also reduced the tumor growth in mouse BC xenografts, indicating that ROR2 promotes BC tumorigenesis in vivo." (PMID 32614787, 2020). "In addition, an analysis of lncRNA-mRNA co-expression indicated that lncRNA is related to ROR2 and MTBP genes, which are tumor-associated protein-coding genes." (PMID 30766487, 2019). "Upregulation of ROR2 is associated with mediating pro-tumorigenic activity (polarized cell migration, invasion, and tumor growth) via the noncanonical Wnt signaling pathway." (PMID 30450096, 2018). "However, recent work reported that Ror2 signaling is able to enhance β-catenin-mediated signaling and proliferation in several tumor types." (PMID 30060804, 2018). "In addition, we found a higher correlation between Ror2 expression in the tumor and tumor grade and between Ror2 and Wnt5a protein expression in tumor tissue, (Sig." (PMID 28427201, 2017).
tumor (continued). "Wnt5a/ROR2 signaling is associated with suppression of β-catenin/TCF-dependent transcriptional activity and down-regulated the expression of cyclin D1 in erythroleukemia cells, suggesting its anti-tumor role on cell proliferation." (PMID 29213214, 2017). "Thus, these additional findings further linked the ability of IFT20 to regulate Golgi ribbon formation with its role in mediating tumor invasiveness and invadopodia formation induced by Ror2 signaling." (PMID 28127051, 2017). "We also examined whether IFT20 regulates the Golgi structure similarly in other tumor cells whose invasiveness might be promoted by the constitutive activation of Ror2 signaling." (PMID 28127051, 2017). "The link between the regulation of the Golgi by IFT20 and its role in mediating tumor invasiveness induced by Ror2 signaling is further strengthened by our additional finding that AKAP450 is also needed for the ability of Ror2 signaling to promote tumor invasion and invadopodia formation." (PMID 28127051, 2017). "These suggested that Wnt5a and Ror2 had played a promoting role in tumor metastasis." (PMID 26608372, 2016). "We observed the expression of Wnt5a and Ror2 in PTL tumor tissues by immunohistochemistry." (PMID 26608372, 2016). "In addition, analysis of 258 patient samples from the publicly available TCGA database found a significant decrease of ROR2 expression in primary tumour samples compared to the normal mucosa, providing strong evidence that ROR2 is downregulated in CRC." (PMID 27440078, 2016). "In SW620 cells, the absence of any change in proliferation and migration following ectopic ROR2 expression may have been because the cell line originated from a secondary tumour site." (PMID 27440078, 2016). "Patients with higher grade tumours were more likely to exhibit high ROR2 expression (p = 0.08)." (PMID 26515598, 2015). "The degree of ROR2 expression was quantified using a two-level grading system, and expression scores were defined as follows: for ROR2 in tumor cells, low expression, 0–39, high expression, 40–300; for stromal cells, low expression, 0–59, high expression, 60–300." (PMID 26259918, 2015). "In addition to Ror2's role in promoting tumor growth, it has been shown to play a role in cell migration and invasion." (PMID 25542006, 2014). "However, Ror2 overexpressing 786-0 cells injected orthotopically into the kidney showed a trend towards increased tumor size." (PMID 25542006, 2014). "However, this analysis left unanswered, if further alterations, in Ror2 expression or sequence would also result in changes in tumor growth or impact the invasive features of these tumors." (PMID 25542006, 2014). "In addition, disruption of the kinase domain of Ror2 through site directed mutagenesis resulted in the abrogation of this increased tumor growth." (PMID 25542006, 2014). "Additionally, we observed a significant increase of average tumor size with increased expression of Ror2." (PMID 25542006, 2014). "In addition to Ror2 promoting tumor growth, we also observed changes consistent with Ror2 dosage correlated effects on both cell migration and invasion." (PMID 25542006, 2014). "To study the relationship between ROR2 promoter hypermethylation and gene expression in vivo, we analysed ROR2 mRNA levels and used tissue microarrays to determine the levels of ROR2 protein in 20 pairs of normal and tumour colon tissues obtained from the same patients." (PMID 20591152, 2010). "However, a separate and compelling body of evidence has shown that in the unique microenvironment of the bone, Wnt5a secreted by osteoblasts acts via ROR2 to suppress canonical Wnt/β-catenin signalling, thereby inducing a state of dormancy in disseminated tumour cells." (PMID 41007281, 2025). "Notably, ROR2 may exhibit context-dependent functions in PCa, acting as either a tumour suppressor or a mediator of therapeutic resistance." (PMID 41007281, 2025). "Likewise, we identified ROR2 among the tumor-exclusive proteins." (PMID 36508875, 2023).